NAE1 (NEDD8 activating enzyme E1 subunit 1)
Diseases named in the same sentence as NAE1 in open-access papers (continued):
Sharing a sentence is not in itself a finding about the gene and the disease.
infertile (1 paper, 2025). "Herein, we report that NAE1 deficiency leads to infertility in male and female mice." (PMID 40083933, 2025). "The aim of this study is to investigate the regulatory mechanisms and physiological functions of NAE1-mediated neddylation during meiosis of mammalian spermatogenesis and its consequential role in infertility." (PMID 40083933, 2025). "After mating with WT mice, both male and female Nae1-SKO mice were completely infertile." (PMID 40083933, 2025). "Nae1-SKO male mice showed a late-pachytene arrest in spermatocytes, resulting in infertility." (PMID 40083933, 2025).
leiomyoma (1 paper, 2022). A well-circumscribed benign smooth muscle neoplasm characterized by the presence of spindle cells with cigar-shaped nuclei, interlacing fascicles, and a whorled pattern. "This revealed two mutations in NEDD8 activating enzyme E1 subunit 1 (NAE1) in one leiomyoma, which was negative for the known leiomyoma driver alterations." (PMID 36068196, 2022).
liver cirrhosis (1 paper, 2015). "Importantly, in a prospective study of patients with liver cirrhosis on ultrasound surveillance at first diagnosis of HCC, global neddylation at protein level as well as Nedd8 and NAE1 gene expression levels were significantly higher in HCC patients with poor prognosis." (PMID 25650664, 2015).
liver diseases (1 paper, 2026). "Bioinformatic analysis further reveals that genetic knockdown of NAE1, UBE2M, and URM1 affects overlapping genes associated with pathways controlling cellular response to stress conditions or with implications in liver diseases." (PMID 42056084, 2026).
liver failure (1 paper, 2022). A liver disease characterized by the liver losing or has lost all of its function. "Together, these data suggest that hepatocyte-specific deletion of NAE1 in adult mice causes fatal liver failure." (PMID 36526632, 2022). "Administration of N-acetylcysteine, a glutathione surrogate and antioxidant, mitigates liver failure caused by hepatic NAE1 deletion in adult male mice." (PMID 36526632, 2022). "The successful amelioration of hepatocyte death and liver failure by GSH-replenishing NAC suggests oxidative stress might be involved in ALF caused by hepatic NAE1 deficiency." (PMID 36526632, 2022).
lupus (1 paper, 2024). "Here, we reported that neddylation inactivation with MLN4924, a specific inhibitor of NEDD8-activating enzyme E1 (NAE1), or genetic abrogation of Ube2m in T cells decreased DN T cell accumulation and attenuated murine lupus development." (PMID 38221551, 2024).
non-small cell lung carcinoma (1 paper, 2020). A group of at least three distinct histological types of lung cancer, including non-small cell squamous cell carcinoma, adenocarcinoma, and large cell carcinoma. "Both cisplatin and carboplatin treatments in A549 and H1299, two human non-small cell lung cancer cell lines, led to the obvious accumulation of UBE2F in a dose-dependent manner, but not other neddylation components (e.g., E1: NAE1 and UBA3; E2: UBE2M; E3: RBX1 and RBX2)." (PMID 33184273, 2020).
Ovarian Tumors (1 paper, 2021). "In addition, in three independent Gene Expression Omnibus (GEO) datasets (GSE14407, GSE26712, and GSE40595), NAE1 was downregulated in ovarian tumors compared with normal ovarian surface epithelium." (PMID 33573293, 2021).
renal fibrosis (1 paper, 2025). A final common manifestation of a wide variety of chronic kidney diseases characterized by glomerulosclerosis and tubulointerstitial fibrosis. "Collectively, this study provides novel insights into NAE1-dependent RhoA neddylation as a key contributor to renal fibrosis in DN." (PMID 39900822, 2025).
Thrombocytopenia (1 paper, 2025). A reduction in the number of circulating thrombocytes. "In particular, the expression of TAG1 (−1.33, −0.12; p ≤ 0.01), SYP (1.67, −0.44; p ≤ 0.03), UBC9 (1.9, −0.51; p ≤ 0.01), NAE1 (−1.18, 0.04; p ≤ 0.03) was altered in newborns with thrombocytopenia." (PMID 40003962, 2025).
cancer (17 papers, 2015 to 2025). A tumor composed of atypical neoplastic, often pleomorphic cells that invade other tissues. "In fact, higher expression of NAE1 was also found to be associated with a worse prognosis in all 18 cancer types (p = 9e−06.; HR 1.2; pHR = 9.2e−06; n = 3244)." (PMID 34853396, 2021). "Interestingly, recent studies showed that the higher expression of COX4NB, E2F4, and NAE1 was associated with poor prognosis in various cancers, suggesting its cancer-promoting role." (PMID 35155261, 2022). "Studies in cancer cells have consistently demonstrated that neddylation directly regulates the stability of a wide range of cell cycle inhibitors, an action that may account for the observed arrest of cardiomyocyte proliferation in NAE1-deficient hearts." (PMID 33391028, 2020). "Targeting NAE1 to destroy NEDD8-mediated protein transformation has become an attractive strategy to manage cancers." (PMID 37640964, 2023). "MLN4924, a potent inhibitor of NAE1, is being evaluated in multiple clinical trials as a novel cancer treatment strategy targeting neddylation." (PMID 37640964, 2023). "To investigate the expression pattern of NAE1 in patients with cancer, we used the Gene Expression Profiling Interactive Analysis (GEPIA) webserver to compare the expression level of NAE1 between tumor and normal tissues in 27 cancer types." (PMID 33573293, 2021). "The neddylation process was inhibited by transfecting cancer cells with NEDD8-targeting siRNAs or by treating the cells with a NAE1 inhibitor MLN4924." (PMID 29301501, 2018). "Moreover, FP-RMS cell lines were among the most sensitive cancer cell lines to both NAE1 and UBA3 genetic depletion as well as NAE pharmacological inhibition with MLN4924 compared to the other cell lines." (PMID 41184241, 2025). "Indeed, overactivation of CRLs has been characterized in tumor growth and progression and the enzymes implicated in the neddylation pathway (e.g., NAE1/UBA3, UBE2M/UBE2F, NEDD8 E3 ligases) are often overexpressed in different human cancers, including MM." (PMID 37460534, 2023). "This revealed 11 samples across six different cancer types with a nonsynonymous mutation in a neddylation-associated gene: four with a UBE2M mutation, five with a NAE1 mutation, one with a NEDD8 mutation, and one with a mutation in the NEDD8-binding domain of CUL3." (PMID 36068196, 2022). "We utilized multilevel TCGA data to investigate whether somatic mutations in UBE2M, NAE1, NEDD8, or the NEDD8-binding domain of CUL3 can be found in cancers with NRF2 activation." (PMID 36068196, 2022). "Importantly, glycine, a metabolite that reflects proliferation rate across cancer cells, was attenuated (21%, p< 0.05) after NAE1 inhibition." (PMID 25650664, 2015). "The first-in-class NAE1 inhibitor, MLN4924, has therapeutic effects on various cancers and is the focus of clinical trials for potential use as an anticancer agent." (PMID 33573293, 2021). "Furthermore, DepMap analyses showed that FP-RMS cell lines are among the most sensitive to both NAE1 and UBA3 CRISPR-mediated knockout as well as to NAE pharmacological inhibition with MLN4924 compared to other cancer cell lines." (PMID 41184241, 2025).
cancer (continued). "While inhibition of neddylation has been shown to induce apoptosis in cancer cells, this effect seems to be cell-type specific, because neither deletion of NAE1 in embryonic hearts nor knockout of CSN8 in postnatal hearts results in prevalent cardiomyocyte apoptosis." (PMID 33391028, 2020). "Because either RhoC depletion or TJSR stimulation effectively blocks cancer cell growth and invasion, we suggest that the targeting of neddylation-dependent TJSR suppressors could be safer than NAE1 inhibition, as it would not stimulate prometastatic RhoC." (PMID 35354476, 2022).
tumor (13 papers, 2014 to 2025). "The fact that TGCTs display the highest levels of NAE1 compared to other human tumour entities or regular tissue suggest neddylation to be potential novel therapeutic option for TGCTs." (PMID 37024667, 2023). "Further, using Firebrowse database analysis higher NAE1 expression in TGCTs compared to other tumour entities were found." (PMID 37024667, 2023). "Of therapeutic relevance, targeting CBFB resulted in decreased tumor burden and bone metastasis, downregulation of bone metastasis markers, and impaired regulation of oxidative stress–related proteins NAE1 and NOS1." (PMID 35903297, 2022). "Concerning HCC, a recent study from Yang and colleagues has reported a correlation between NAE1 expression and histologic grade, tumor size as well as clinical stage of HCC in patients." (PMID 31817100, 2019). "Specifically, 90% (36/40) of the OS tumor samples had high levels of NAE1, and 95% (38/40) had high levels of Ube2M." (PMID 27223074, 2016). "We first demonstrated that the neddylation pathway is activated in most OS cells, as evidenced by comparative analysis of NAE1 and Ube2M levels in OS tumor tissues and in healthly bone tissues." (PMID 27223074, 2016). "Patients with high expression of NAE1 were 1.62 times more likely to suffer from tumor recurrence than those with low expression (HR, 1.62; 95%CI, 1.13-2.33), similar to the predictive power of tumor vascular invasion (HR, 1.65; 95%CI, 1.12-2.43; P = 0.011)." (PMID 25229838, 2014). "Here, we report that the NAE1 and UBA3 genes encoding the two subunits of the NEDD8-activating enzyme (NAE) heterodimer are upregulated in FP-RMS patients compared to healthy skeletal muscle tissues and highly expressed in RMS among several tumor types." (PMID 41184241, 2025). "NAE1 expression is highest in TGCTs compared to other tumour entities and normal tissues." (PMID 37024667, 2023). "Higher NAE1 expression was correlated with larger tumor size, poorer Edmondson’s grade, presence of microvascular invasion, poorer TNM, and poorer BCLC stage, and higher UBE2M expression was correlated with multiple tumors and the presence of microvascular invasion." (PMID 29846044, 2018). "In this study, we show that both NAE1 and UBA3 are overexpressed in FP-RMS patients compared to healthy muscle tissues and several other tumor types." (PMID 41184241, 2025). "Although NEDD8, NAE1, and UBC12 expression significantly correlated with tumor recurrence, their expression intensities were largely independent of conventional clinicopathologic features, like tumor size, vascular invasion, lymph node metastasis, intrahepatic metastasis and TNM stage." (PMID 25229838, 2014). "It is interesting that, the expressions of MYBL2, CSE1L, and most neighbors of NAE1 (59/63) are significantly different between tumor and normal tissues (P-value < 0.05, Wilcoxon rank sum test with continuity correction), but as a link gene NAE1 is not differentially expressed." (PMID 36266635, 2022). "Of note, subgroup analysis showed that the prognostic value of NEDD8, NAE1, and UBC12 also existed in patients with relatively early stage disease, such as patients with small tumor, or with no vascular invasion, or in early TNM stages (I+II)." (PMID 25229838, 2014). "Moreover, renal biopsies from patients with biopsy-proven DN exhibited elevated NAE1 and NEDD8 expression levels compared with normal kidney tissues obtained from tumor nephrectomy patients without renal disease." (PMID 39900822, 2025).
infection (3 papers, 2019 to 2026). The state of being infected such as from the introduction of a foreign agent such as serum, vaccine, antigenic substance or organism. "To identify whether hepatocyte reprogramming also occurred in vitro when neddylation is inhibited, we deleted NAE1 in Nae1f/f primary hepatocytes via Cre adenoviral (pAd-Cre) infection." (PMID 36526632, 2022). "NAE1 and FGFR1 were important for infection by an early ancestral Wuhan strain as well as more recent omicron variants, indicating that neddylation and FGFR signaling are critical host processes for this coronavirus." (PMID 41585476, 2026). "The screen revealed NAE1 and FGFR1 as key contributors to infection." (PMID 41585476, 2026).
benign tumors (1 paper, 2021). "Moreover, using GEO datasets (GSE17308), we confirmed that the expression of NAE1 was slightly decreased in benign tumors and further decreased in invasive cancers compared with normal tissues." (PMID 33573293, 2021).
NAE1 also shares sentences with these, for which no sentence is quoted: colorectal cancer (5 papers); dilated cardiomyopathy (2); esophageal squamous cell carcinoma (2); hepatocellular carcinoma (2); lung carcinoma (2); Parkinson disease (2); cardiac hypertrophy (1); cervical carcinoma (1); dementia (1); endothelial dysfunction (1); familial chylomicronemia syndrome (1); gastric cancer (1); head and neck tumor (1); Huntington disease (1); intrahepatic cholangiocarcinoma (1); leukemia (1); lung adenocarcinoma (1); lung squamous cell carcinoma (1); lymph node metastasis (1); melanoma (1); nasopharyngeal carcinoma (1); neuroblastoma (1); peripheral neuropathy (1); Premature ovarian insufficiency (1); renal carcinoma (1); renal disease (1); Sepsis (1); serous ovarian cancer (1); transient cerebral ischemia (1); urothelial carcinoma (1).